TRIB1 (tribbles pseudokinase 1)
Diseases named in the same sentence as TRIB1 in open-access papers (continued):
Sharing a sentence is not in itself a finding about the gene and the disease.
hepatocellular carcinoma (11 papers, 2015 to 2024). A malignant tumor that arises from hepatocytes. "To examine how prevalent this relationship was, we examined the impact of TRIB1 silencing in another widely studied human hepatoma cell line, HuH-7 cells where TRIB1 suppression led to reduced HNF4A protein." (PMID 28717196, 2017). "TRIB1 plays a role in hepatocellular carcinoma (HCC) as well, as evidenced by its upregulation in HCC cell lines and tumor tissues." (PMID 38791967, 2024). "In the present study, we identified, through a high-throughput qRT-PCR screen, small-molecule upregulators of TRIB1 expression and characterized the effects of the lead compound, BRD0418, on lipid metabolism in HepG2 hepatoma cells." (PMID 25811180, 2015). "Hepatic overexpression of Trib1 in mice reduced the secretion of VLDL particles from the liver into the bloodstream and, consistent with this observation, overexpression of TRIB1 in human hepatoma cells reduced apoB secretion." (PMID 25811180, 2015).
Obesity (11 papers, 2012 to 2026). Accumulation of substantial excess body fat. "We conclude that this genetic information on human TRIB1-3 shows an inverse association between sleep duration and obesity, validating our observations in flies." (PMID 37083954, 2023). "TRB1 and TRB3 have both been linked to obesity and related phenotypes, with TRIB1 gene expression linked to adipose tissue inflammation and TRB3 gene expression associated with insulin resistance." (PMID 22589742, 2012). "Additionally, Piwil1, Spata3, and Trib1 have previously been associated with obesity and its complications." (PMID 40944384, 2025). "These sets of experimental evidence suggest that TRIB1 may be able to restore obesity and hyperlipidemia caused by circadian rhythm disorders by regulating the discipline gene." (PMID 34539875, 2021). "Several of the identified loci have been implicated in ASCVD risk factors such as circulating lipids (LPA-PLG, APOE, TRIB1, KANK2), diabetes (CDKN2B-AS1, IGF2BP1) and obesity (LEPR, IGF2BP1)." (PMID 40164586, 2025). "We used data from the UK Biobank and an in silico workflow to screen for associations between SNPs in TRIB1-3 and alterations in either sleep duration or waist-to-hip ratio (WHR), a readout of obesity, accounting for covariates." (PMID 37083954, 2023). "TRIB1 knockout reduces the expression of cytokine genes in white adipocytes and prevents high-fat diet-induced obesity." (PMID 34539875, 2021). "Controlling the activity of TRIB1 through diet or pharmacotherapy can improve the thermogenic function of brown and beige fat as a new potential treatment strategy for obesity." (PMID 34811364, 2021). "Our findings add TRIB1 as an additional mediator of its anti-obesity actions." (PMID 41588470, 2026). "TRIB1 knockout mice exhibit obesity and increased lipid accumulation in their livers." (PMID 36873932, 2023). "Because RAP2A and TRIB1 levels are increased with obesity in mice and humans, the basal activity of the G protein may drive Trib1 induction and subsequent downregulation of β3-AR in vivo." (PMID 34847077, 2022). "Taken together, our results indicate that Trib1 regulates the function of mitochondria and brown adipocytes in mice, suggesting its potential as a new target for the treatment of metabolic diseases such as hyperlipidaemia, fatty liver, and obesity." (PMID 34811364, 2021). "Previous studies have reported that Trib1 haploinsufficiency protects against high-fat diet-induced obesity in mice, which was considered to be related to inhibition of the high-fat diet-mediated increase in proinflammatory gene expression due to Trib1 knockout." (PMID 34811364, 2021). "Trib1-knockout mice exhibited obesity and impaired BAT thermogenesis." (PMID 34811364, 2021). "Collectively, these findings support a model in which TRIB1 serves as a critical mediator through which berberine coordinates leptin signaling and mitochondrial function, providing mechanistic insight that may inform future strategies for obesity intervention." (PMID 41588470, 2026). "We further posited that TRIB1 could facilitate C/EBPα ubiquitination, reduce leptin synthesis, and alleviate mitochondrial fragmentation associated with DRP1 activity, thereby improving leptin signaling and mitochondrial function in obesity." (PMID 41588470, 2026). "In the early stage, we established TRIB1 knockout mice, selected wild-type (WT) and knockout (KO) mice of the same litter and gave them a HFD and berberine treatment, and measured leptin levels and obesity-related phenotypes." (PMID 41588470, 2026). "Furthermore, both TNF-α and CL-316243 in vitro and obesity in vivo induced Cebpb in our RNA-Seq data sets, suggesting that CEBPB may be driving Trib1 induction." (PMID 34847077, 2022). "In addition, whether the specific overexpression of Trib1 in the mouse BAT can enhance heat production by enhancing mitochondrial function and prevent obesity must be further investigated." (PMID 34811364, 2021).
dyslipidemia (10 papers, 2011 to 2025). "Previous studies indicated that inhibition of Trib1 caused atherogenic dyslipidemia, while overexpression or rescue of Trib1 remodeled lipid metabolism homeostasis." (PMID 36714195, 2023). "GWAS studies have repeatedly confirmed that TRIB1 gene polymorphisms were associated with dyslipidemia, and several studies had shown that TRIB1 gene variants can increase the risk of CHD." (PMID 31470861, 2019). "Variants of TRIB1 (i.e., rs17321515 and rs2954029) may serve as causal genetic markers for dyslipidemia and CAD in Asian population." (PMID 36714195, 2023). "In our study, the genotype distribution of rs2954029 in TRIB1 was significantly different between dyslipidemia female patients and healthy controls." (PMID 37147786, 2023). "In this study, we constructed GRSs composed 7 genetic variants (ANGPTL3 rs10889353, APOB rs7557067, GCKR rs780092, C2orf16 rs1919127, TRIB1 rs2954029, FADS1-FADS2-FADS3 rs174547, and APOA5 rs2266788) associated with dyslipidemia using GWAS studies." (PMID 33339179, 2020). "TRIB1 encodes the protein tribbles homolog one that is involved in many human diseases, including myeloid leukemia, Crohn's disease, NAFLD, dyslipidemia, and CAD, which is part of mitogen‐activated protein kinases and may regulate lipid metabolism." (PMID 37147786, 2023). "However, despite the substantial evidence linking TRIB1 with dyslipidemia in humans, currently little is known about the regulation of endogenous TRIB1 expression and its relationship with nutritional factors." (PMID 31666640, 2019). "While the CAD/dyslipidemia-associated etiology is unlikely to implicate changes in TRIB1 protein stability, increasing the latter modestly by targeted pharmacological interventions may still offer a means to harness the protective functions of TRIB1." (PMID 27019349, 2016). "Also, our results did not establish a cause–effect relationship between TRSP1 and TRIB1 polymorphisms and ACS or with dyslipidemia; the study only showed a statistical correlation between minor allele risk of developing ACS and plasma lipids levels." (PMID 40563858, 2025).
glioma (9 papers, 2015 to 2024). A benign or malignant brain and spinal cord tumor that arises from glial cells (astrocytes, oligodendrocytes, ependymal cells). "We and others have shown that TRIB1 mRNA and protein levels are upregulated by radiation and temozolomide treatment in glioma cells, causing a decrease in treatment-induced cell death." (PMID 38791967, 2024). "To further evaluate TRIB1 as a biomarker in glioma, we looked at the association of TRIB1 gene expression with clinical outcomes using respective GBM and LGG patient cohorts." (PMID 37528172, 2023). "We next investigated the association of Trib1 with the development of radioresistance in glioma cells." (PMID 26521947, 2015). "Trib1-deficient glioma cells showed an enhanced response to irradiation-induced apoptosis." (PMID 26521947, 2015). "The data have revealed that Trib1 plays a critical role in the development of radioresistance in glioma cells." (PMID 26521947, 2015). "In line with those published data, our results suggest that Trib1 is also involved in the pathogenesis of cancer by conferring glioma cells the ability of radioresistance." (PMID 26521947, 2015). "Our data reveal a new member of the molecular pool of radioresistance inducer, the Trib1, which plays a critical role in the radioresistance development in glioma cells in the repeated exposures to small doses of radiation." (PMID 26521947, 2015). "Similar to those previous studies, we identified that Trib1 played a critical role in the radioresistance of glioma cells." (PMID 26521947, 2015). "The results showed that human glioma cells expressed a low level of Trib1, which was significantly up regulated by exposure to small doses (2 Gy/day for 4 days) of irradiation." (PMID 26521947, 2015). "The results showed that exposure to irradiation markedly increased the expression of Trib1 in glioma cells, which was abolished by the presence of butyrate sodium." (PMID 26521947, 2015). "In conclusion, the Trib1 plays a critical role in the development of radioresistance of glioma cells." (PMID 26521947, 2015). "Increased TRIB1 mRNA levels have been correlated with poor overall survival of glioma patients." (PMID 38791967, 2024). "We wondered if Trib1 contributed to the HDAC1 phosphorylation in glioma cells." (PMID 26521947, 2015). "The data indicate that human glioma cells express Trib1, which can be up regulated by irradiation, which may be associated with glioma cell activities in a radiation environment." (PMID 26521947, 2015). "Furthermore, we found that interference with the signal transduction pathway of the Trib1-induced radioresistance in glioma cells resulted significant enhancement of the radiosenstive of the cells." (PMID 26521947, 2015). "The results showed that the Trib1 was detected in the human glioma cells, which was markedly up regulated by exposing to low doses (2 Gy/day for 1–4 days, or at graded doses for 4 days) irradiation in a time-dependent manner and in an irradiation dose-dependent manner." (PMID 26521947, 2015). "Whether irradiation can regulate Trib1 expression in glioma cells is unclear." (PMID 26521947, 2015). "The data showed that after repeated exposures to small doses of irradiation, the apoptotic glioma cells were reduced markedly as compared to control glioma cells, accompanying the increases in HDAC1 phosphorylation, in which Trib1 was required." (PMID 26521947, 2015).
glioma (continued). "In contrast, glioma cells lacking TRIB1 exhibit enhanced responses to radiation-induced apoptosis." (PMID 34539875, 2021).
hyperlipidemia (8 papers, 2012 to 2024). "Tribbles 1 (Trib1) has been detected in murine plaque-resident macrophages, and variants at the TRIB1 locus have been associated with increased risk of hyperlipidemia and atherosclerotic disease in multiple populations." (PMID 31692955, 2019). "First, we wanted to ascertain the consequences of altered myeloid Trib1 levels in metabolic tissues as this gene has been identified as a risk locus for hyperlipidaemia in a number of GWAS analyses but its molecular mechanism impacting on lipid homeostasis is still incompletely understood." (PMID 33329538, 2020). "Recent studies have shown that TRIB1 can regulate acute and chronic inflammation by affecting the secretion of inflammatory factors, which is closely related to the occurrence of hyperlipidemia and cardiovascular diseases." (PMID 34539875, 2021). "The results summarized above demonstrated that Trib1 knockout leads to mitochondrial dysfunction in the BAT of mice, causing impaired heat production and hyperlipidaemia." (PMID 34811364, 2021). "Our results showed that the Trib1 knockout can damage adaptive thermogenesis and induce hyperlipidaemia and fatty liver in mice." (PMID 34811364, 2021).
diabetes (6 papers, 2017 to 2026). "Several other genes displaying inverted correlations have previously been linked to diabetes (7/18), either by functional studies (TRIB1, glucose metabolism; NFKBIA, insulin resistance pathway) or as candidate disease genes in GWAS or gene expression studies (TMPPE, PRTG, and ZNF319)." (PMID 31159854, 2019).
myocardial infarction (6 papers, 2013 to 2024). Gross necrosis of the myocardium, as a result of interruption of the blood supply to the area, as in coronary thrombosis. "Polymorphisms in TRIB1 are associated with an improved lipid profile and decreased risk of myocardial infarction in humans, and Trib1 knockout mice have elevated plasma triglyceride and cholesterol levels." (PMID 23813869, 2013).
colorectal cancer (5 papers, 2017 to 2021). A primary or metastatic malignant neoplasm that affects the colon or rectum. "In colorectal cancer, TRIB1 overexpression is significantly associated with decreased disease-free survival." (PMID 34205360, 2021). "The need for further investigation is further emphasised by the impact of TRIB1 amplification and overexpression on patient outcome in breast and colorectal cancers." (PMID 34205360, 2021). "In this review, we discuss the state-of-knowledge for TRIB1, TRIB2 and TRIB3 in the development and progression of colorectal cancer." (PMID 34198908, 2021). "Tribbles pseudokinase family members (TRIB1 (C8FW or SKIP1), TRIB2 (C5FW) and TRIB3 (NIPK, SKIP3 or LKW)) might be biomarkers of interest in colorectal cancer." (PMID 34198908, 2021).
Hepatic steatosis (5 papers, 2013 to 2024). Steatosis is a term used to denote lipid accumulation within hepatocytes. "The TRIB1 locus has been linked to both cardiovascular disease and hepatic steatosis." (PMID 28717196, 2017). "The majority of the variants were associated with hepatic lipid metabolism and fatty liver disease, with certain variants (in APOE and TRIB1) displaying significantly larger effects on NAFLD compared with cirrhosis." (PMID 38632349, 2024). "Other previously unreported variants associated with lipid traits and fatty liver disease, including rs2792735 in GPAM, rs2980888 in TRIB1, rs13389219 in COBLL1, rs8178824 in APOH and rs339969 in ICE2." (PMID 38632349, 2024). "Five fatty liver disease-associated SNPs (rs780094 (GCKR), rs2281135 (PNPLA3), rs8418 (PNPLA3), rs58542926 (TM6SF2), rs2980875 (TRIB1)) passed the significance threshold of <0.05 and were directionally consistent with previous studies." (PMID 30978214, 2019). "This final list includes six genes associated with ALT elevation and/or hepatic steatosis (MAPK10, CPN1, TRIB1, PNPLA3, SAMM50 and MICAL3)." (PMID 23813869, 2013). "We also found that variants in TRIB1, TM6SF2 and APOE had stronger effects on NAFLD compared with cirrhosis, indicating that they may primarily exert their effect on cirrhosis via fatty liver disease." (PMID 38632349, 2024).
non-alcoholic fatty liver disease (5 papers, 2014 to 2025). "In contrast, the genes PNPLA3 (adiponutrin), GCKR (glucokinase regulator) and TRIB1 (tribbles homolog 1) were associated with fibrosis phenotypes in non-alcoholic fatty liver disease, with PNPLA3 demonstrating the most consistent effects across studies." (PMID 24586654, 2014). "Among the 4 SNPs predicting ALT, rs2954021 (TRIB1) predicts both ALT and ALP, and rs738409 (PNPLA3) is highly associated with non-alcoholic fatty liver disease." (PMID 32045441, 2020).
non-small cell lung carcinoma (5 papers, 2017 to 2024). A group of at least three distinct histological types of lung cancer, including non-small cell squamous cell carcinoma, adenocarcinoma, and large cell carcinoma. "The C/EBPβ transcription factor also regulates TRIB1 expression, notably in anaplastic large cell lymphoma and cisplatin-treated non-small cell lung cancer (NSCLC)." (PMID 35205759, 2022).
type 2 diabetes (5 papers, 2011 to 2022). "Interestingly, the predominant Q84 glutamine variant is unique to the genus Homo, as the rare R variant associated with predisposition to human Type 2 diabetes is found at this position in Trib3 in other vertebrates and in Trib1 and Trib2 in all vertebrates." (PMID 29025897, 2017).
familial hypercholesterolemia (4 papers, 2015 to 2020). An inheritable form of hyperlipidemia, in which there are excess lipids in the blood. "TRIB1 (Tribbles Pseudokinase 1) is a protein coding gene and related ailments were megakaryocytic leukemia and familial hypercholesterolemia." (PMID 33339179, 2020). "Three individual genes (MIA3, CNNM2, and TRIB1) and 44 gene pairs overlap between MI and hypercholesterolemia." (PMID 27640124, 2016). "The same approach applied to hypercholesterolemia identified three genes also associated with MI: MIA3, CNNM2, and TRIB1; suggesting their role in MI could be mediated through lipid metabolism." (PMID 27640124, 2016).
colon cancer (3 papers, 2017 to 2022). "Previous studies reported TRIB1 as an oncogene 24-26, including in prostate and colon cancer but its mechanistic contribution to tumorigenesis is yet to be fully understood." (PMID 35664073, 2022). "Conversely, silencing TRIB1 expression by shRNA against TRIB1, in both SW480-TRIB1 and COLO320HSR cells, reduced the level of cell migration and invasion, establishing a role for TRIB1 in colon cancer cells motility." (PMID 34198908, 2021). "While for TRIB1, gene amplification might partially support its increased levels not only in colon, but also in other types of cancer, the mechanism behind TRIB2 overexpression in colon cancer patients is still unclear." (PMID 34198908, 2021).